NPM1 (nucleophosmin 1)
Diseases named in the same sentence as NPM1 in open-access papers (continued):
Sharing a sentence is not in itself a finding about the gene and the disease.
anaplastic large cell lymphoma (102 papers, 2010 to 2026). Anaplastic large cell lymphoma (ALCL) is a rare and aggressive peripheral T-cell non-Hodgkin lymphoma, belonging to the group of CD30-positive lymphoproliferative disorders, which affects lymph nodes and extranodal sites. "EML4-ALK is commonly associated with non-small cell lung cancer; NPM1-ALK is most frequent in anaplastic large cell lymphoma." (PMID 30675517, 2019). "The NPM1-ALK (anaplastic lymphoma kinase) fusion protein is the hallmark of ALK-positive anaplastic large cell lymphoma." (PMID 29855342, 2018). "Indeed, mutations in the NPM1 gene has been observed in Anaplastic large-cell lymphoma (ALCL), Acute promyelocytic leukemia (APL) and Acute myeloid leukemia." (PMID 36532440, 2022). "Clusters 3.4 and 3.6 also featured upregulation of genes implicated in large cell lymphomas, and notably overlapping with several genes enriched in RT tumors compared to matched CLL precursors, including Birc5, Cdk1, Mki67, and Npm1." (PMID 36609611, 2023). "Currently, the best studied ALK fusions are NPM1-ALK in anaplastic large-cell lymphoma (ALCL) and EML4-ALK in non-small cell lung cancer (NSCLC), which harbor ALK fusions in approximately 5% of cases." (PMID 35204520, 2022). "Initial investigations into the role of NPM1 mutations in AML followed on from the study of the chimeric fusion protein NPM-ALK which is present in 30–50% of advanced anaplastic large-cell lymphoma cases." (PMID 34576201, 2021). "ALCL (Anaplastic Large Cell Lymphoma) is a rare but highly aggressive T-cell non-Hodgkin lymphoma that originates from a chromosomal translocation that produces the fusion protein NPM1-ALK, a constitutively active tyrosine kinase." (PMID 32676504, 2020). "ALK’s most common fusion partners are the NPM1 gene in anaplastic large cell lymphoma and EML4 in epithelial tumors." (PMID 31007851, 2019). "The oncogenic fusion protein of anaplastic lymphoma kinase (ALK) with nucleophosmin 1 (NPM1) in anaplastic large cell lymphoma leads to the activation of multiple intracellular signal transduction pathways including PI3K–AKT, MAPK/ERK, mTOR, STAT3, and STAT5B." (PMID 31690038, 2019). "First discovered as a partner to Nucleophosmin 1 (NPM1) in the NPM-ALK fusion oncoprotein of Anaplastic Large Cell Lymphoma (ALCL), Anaplastic Lymphoma Kinase (ALK) is a receptor tyrosine kinase and a member of the insulin receptor superfamily." (PMID 29642598, 2018). "ALK-fusion genes have been observed in anaplastic large cell lymphomas (ALCLs) as a nucleophosmin 1 (NPM1)-to-ALK fusion gene, and in lung adenocarcinomas (lung ADCs) as an EML4-to-ALK fusion gene." (PMID 29760954, 2018). "ALK rearrangements resulting in an activated ALK fusion protein were first identified in 1994 with the observation of nucelophosmin (NPM1)-ALK in anaplastic large cell lymphoma." (PMID 26062823, 2015). "Many of these breakpoints corresponded to known gene fusions, including BCR/ABL1 in CML, FIP1L1/PDGFRA in eosinophilic leukemia, and NPM1/ALK in anaplastic large cell lymphoma (ALCL)." (PMID 23637631, 2013). "Karpas 299 is derived from Anaplastic large cell lymphoma with a NPM1-ALK fusion." (PMID 35077445, 2022). "Anaplastic large-cell lymphoma (ALCL) patients’ NPM1 fusion with ALK was first discovered in 1994." (PMID 35557858, 2022). "Interestingly, in anaplastic large-cell lymphoma cells, the cytoplasmic fraction of the NPM1-ALK fusion protein is solely responsible for inducing apoptosis by engaging the DNA-damage response." (PMID 27553022, 2016). "Certain genes are tumor-type specific: EML4-ALK fusions have been detected in lung cancer samples, and nucleophosmin (NPM1)-ALK fusions were found in anaplastic large cell lymphoma (ALCL)." (PMID 31513617, 2019). "In fact, ALK was first discovered in anaplastic large cell lymphoma (ALCL) in the form of a fusion protein, NPM1-ALK." (PMID 30941048, 2019).
anaplastic large cell lymphoma (continued). "ALK is a receptor tyrosine kinase that was first identified as a fusion gene with nucleophosmin 1 (NPM1-ALK), via a 2;5 chromosomal translocation in anaplastic large-cell lymphoma." (PMID 31278140, 2019). "As proof-of-principle, we applied hiBA-FISH to measure the number of chromosome breaks at the NPM1 and ALK gene loci and the frequency of the anaplastic large cell lymphoma-specific NPM1-ALK translocation upon irradiation." (PMID 26313373, 2015). "Other studies on anaplastic large cell lymphoma, the most common T-cell NHL in children, found that tumor progression was primarily driven by a fusion product between ALK and mainly nucleophosmin 1 (NPM1) called NPM-ALK." (PMID 36172151, 2022). "Many translocations have been found with this ALK gene, including EML4:ALK which is responsible for approximately 3-5% of non-small-cell lung cancer(NSCLC), RANBP2:ALK, TPM4:ALK in inflammatory myofibroblastic tumor, NPM1:ALK, ATIC:ALK, TFG:ALK in anaplastic large cell lymphoma, and so on." (PMID 24564548, 2013). "In 1994, ALK was originally discovered in an anaplastic large cell lymphoma (ALCL) cell line, in which the ALK gene was fused with the nucleophosmin 1 (NPM1) gene, resulting in a new fusion protein, NPM‐ALK." (PMID 34845836, 2022).
myelodysplastic syndrome (46 papers, 2010 to 2026). A clonal hematopoietic disorder characterized by dysplasia and ineffective hematopoiesis in one or more of the hematopoietic cell lines. "Although an increase in blasts exists in most AML cases with mutated NPM1, if the blast count is < 10%, the diagnosis is changed to “AML with NPM1” in WHO2022 and “NPM1-mutated myelodysplastic syndrome (MDS)” in ICC." (PMID 38616211, 2024). "In contrast to AMLs in which NPM1 mutations are frequent, myelodysplastic syndromes (MDS) only rarely display NPM1 mutations." (PMID 37509445, 2023). "Given associations between colitis and myelodysplastic syndrome (in which nucleophosmin 1 is often mutated), the authors here look at the contribution of nucleophosmin 1 to colitis, showing that it is important for protection mediated by ILC3s owing to effects on mitochondrial metabolism." (PMID 39103576, 2024). "Menin inhibitors were reported to prevent the transformation of Npm1-mutated mouse hematopoietic progenitors into leukemic cells, implying that they could also be effective in Npm1-mutated preleukemia." (PMID 36008542, 2022). "NPM1 insertional mutations have also been found in myeloid neoplasms including myelodysplastic syndrome (MDS), myeloproliferative neoplasm (MPN), and chronic myelomonocytic leukaemia (CMML)." (PMID 36834572, 2023). "The 2016 WHO classification revised the myelodysplastic syndrome (MDS)-related cytogenetic abnormalities: del (9q) was removed and patients with mutated NPM1 or biallelic CEBPA were recategorized as having recurrent genetic abnormalities." (PMID 33938209, 2021). "There are emerging data suggesting that cases previously classified as Myelodysplastic syndromes (MDSs) or MDS/myeloproliferative neoplasms (MPNs) with NPM1 progress to AML shortly." (PMID 40647396, 2025). "The World Health Organization (WHO) 5th edition classifies AML with mutated NPM1 as a distinct entity, despite the blast count, perhaps due to the rapid time to progression from myelodysplastic syndrome (MDS) or myelodysplastic syndrome/myeloproliferative neoplasm (MDS/MPN)." (PMID 39200232, 2024). "The NPM1 gene is located on chromosome 5q35, which is occasionally deleted in myelodysplastic syndrome (5q−MDS)." (PMID 25617756, 2015). "In addition to its role in shaping the AML microenvironment, cell-intrinsic inflammation is induced by NPM1 perturbation in mice, leading to myelodysplastic syndrome-like phenotypes and driving progression to AML." (PMID 40702544, 2025). "It usually is a “de novo AML”, but may, in some cases, arise as the clonal evolution of a myelodysplastic syndrome (MDS), with NPM1 mutations being reported in up to 14% of MDS-derived AML." (PMID 39457595, 2024). "Conversely, a previous history of myelodysplastic syndrome (MDS) or MRC-related cytogenetic abnormalities, even in the presence of NPM1 mutation, are diagnostic of AML-MRC." (PMID 33879827, 2021). "In addition, NPM1 maps to the 5q35 locus of chromosome 5, a region that is deleted in a subset of patients with de novo myelodysplastic syndromes (MDS)." (PMID 35054502, 2022). "Non-acute myeloid neoplasms (MNs) with NPM1 mutations (NPM1mut-MNs) pose a diagnostic and therapeutic dilemma, primarily manifesting as chronic myelomonocytic leukemia (CMML) and myelodysplastic syndromes (MDS)." (PMID 38398096, 2024). "Currently, no amplification of the NPM1 gene has been detected in human tumors, but the gene is deleted in myelodysplastic syndromes." (PMID 36280841, 2022).
myelodysplastic syndrome (continued). "Nowadays, there is no agreement in the literature on whether non-acute NPM1-mutated MNs (NPM1mut-MNs) such as chronic myelomonocytic leukemia (CMML) and myelodysplastic syndromes (MDS) with NPM1mut should be diagnosed and treated as AML." (PMID 38398096, 2024). "The patient who did not relapse developed a NPM1-negative myelodysplastic syndrome." (PMID 26486081, 2015). "Molecular testing for FLT3, NPM1, and CEBPA was not performed, given the picture of antecedent myelodysplastic syndrome (MDS)." (PMID 26114018, 2014).
myeloid neoplasm (45 papers, 2010 to 2026). Proliferation of myeloid cells originating from a primitive stem cell. "NPM1-mutated AML has been recognized as a distinct entity in the 2017 World Health Organization (WHO) classification of myeloid tumors." (PMID 40603297, 2025). "Even when NPM1mut is tightly associated with de novo AML, on rare occasions, NPM1 mutations can emerge in other myeloid neoplasms as secondary mutations, ultimately contributing to the development of AML, as suggested by clinical studies and mouse models." (PMID 38398096, 2024). "We describe the clinicopathologic features of eight patients with atypical presentation of NPM1-mutated myeloid neoplasms (MN) and review the literature." (PMID 38398096, 2024). "It is unclear if NPM1 mutations remain a positive prognostic indicator within secondary AMLs evolving from a prior myeloid neoplasm." (PMID 37509445, 2023). "Myeloid neoplasms with NPM1 mutations and <20% blasts are characterized by an aggressive clinical course and a rapid progression to AML." (PMID 35054502, 2022). "The latest updates of the World Health Organization (WHO) classification of myeloid neoplasm recognized AML with mutated NPM1 as a distinct diagnostic entity." (PMID 35054502, 2022). "The best approach to the pathologic diagnosis and clinical management of myeloid neoplasms with NPM1 mutation and less than 20% blasts is still unclear." (PMID 35054502, 2022). "Myeloid neoplasms with NPM1 mutations occurred in younger patients and were more commonly associated with a normal karyotype when compared with NPM1 wild-type cases." (PMID 35054502, 2022). "NPM1-mutated AML have been recognized as a distinct entity in the last WHO myeloid neoplasm classification related to favorable outcomes." (PMID 34885010, 2021). "Currently, NPM1 mutations are known for their favorable prognosis role and have been included in the stratification of the World Health Organization from 2016 or myeloid neoplasms." (PMID 33255417, 2020). "According to the cBioPortal database reporting of 4 studies of adult MDS and AML patients, U2AF1 mutations occur in 5% and NPM1 is mutated in 22% of all myeloid malignancy patients." (PMID 33137094, 2020). "Indeed, at least one pathogenic mutation (WT1, FLT3-ITD, IDH2 or PTPN11 mutation) has been identified in all the reported myeloid tumors harboring NPM1::MLF1." (PMID 39443736, 2024). "Nevertheless, NPM1 gene mutations rarely occur in other myeloid neoplasms (MNs) with <20% blasts." (PMID 38398096, 2024). "Selective XPO1 inhibitors (selinexor, eltanexor) show preferential activity in NPM1-mutated, DEK::NUP214-positive and SF3B1-mutated myeloid neoplasms." (PMID 42071259, 2026). "(It is important to highlight that, in their series, some cases of NPM1 myeloid neoplasm had less than 5% of blasts, and some inside this group had blast percentages as low as 1%)." (PMID 40421449, 2025). "A possible explanation for this finding is probably related to the fact that most patients with NPM1 myeloid neoplasm (33 out of 45 patients) were treated upfront with hypomethylating agents, and 13 of them progressed to AML at a median of 5.9 months." (PMID 40421449, 2025). "ASXL1mt in myeloid neoplasms were considered to be ubiquitously accompanied by mutations of RUNX1, SRSF2, STAG2, NRAS, or IDH2, in addition to wild‐type NPM1 and FLT3,14, 21, 22, 28 which was aligned with the mutation profile in our cohort." (PMID 38146893, 2023). "In myeloid neoplasms other than AML, NPM1 mutation has been detected in MDS (2%) and myelodysplastic/myeloproliferative neoplasms (MDS/MPN) (3%), with MDS/MPN represented by mainly chronic myelomonocytic leukemia (CMML)." (PMID 35054502, 2022).
myeloid neoplasm (continued). "Other genes commonly mutated in myeloid neoplasms, such as FLT3 (fms like tyrosine kinase 3), DNMT3A (DNA Methyltransferase 3 Alpha), IDH1/2 (Isocitrate Dehydrogenase (NADP(+)) 1/2), NPM1 (Nucleophosmin 1), and RUNX1, are rare and almost mutually exclusive." (PMID 35054439, 2021). "At the same time, SF3B1 (Splicing Factor 3b Subunit 1), U2AF1 (U2 Small Nuclear RNA Auxiliary Factor 1), NPM1, and FLT3 are rarely mutated in GATA2-mutated myeloid neoplasms." (PMID 35054439, 2021). "In the 2016 updated World Health Organization (WHO) classification of myeloid neoplasms, AML with nucleophosmin (NPM1) mutations was defined as a distinct subtype." (PMID 34615546, 2021). "Nucleophosmin 1 (NPM1) is one of the most frequently mutated genes in AML and its mutation is exclusively restricted to myeloid malignancies." (PMID 34944812, 2021). "Strikingly, NPM1 mutations rarely occur outside of myeloid malignancies (i.e., MDS and AML), suggesting that NPM1 plays a unique role in the differentiation and/or proliferation of myeloid cells." (PMID 33137094, 2020). "NPM1-mutated AML has earned recognition as a distinct entity among myeloid tumors, but the absence of a thoroughly established tool for its morphological analysis remains a notable gap." (PMID 40603297, 2025). "This change resulted in an increase in the diagnosis of certain subtypes (such as AML with NPM1 and FLT3-ITD mutations), while other subtypes (such as AML with bone marrow proliferative abnormalities and treatment-related myeloid neoplasms) gained new recognition." (PMID 37193689, 2023). "In contrast, the same concept does not apply for the finding of NPM1 gene mutation: myeloid neoplasms with less than 20% blasts do not meet current criteria for a diagnosis of NPM1-mutated AML." (PMID 35054502, 2022). "Unlike most myeloid mutations, NPM1 is remarkable for its specificity to a subtype of AML that is recognized as a specific diagnostic entity by the current WHO classification of myeloid neoplasms." (PMID 35054502, 2022). "Studies have validated that both FLT3-ITD and FLT3D835Y are driver mutations in AML that cause myeloid neoplasms in murine models, FLT3-ITD occurs in about 25% of AML patients and represents an unfavorable prognosis unless nucleophosmin 1 (NPM1) mutations are present." (PMID 32817792, 2020). "Several zebrafish models associated with myeloid malignancies have been previously reported, including transgenic zebrafish that exhibit K-RASG12D, NUP98-HOXA9, Stat5 (H298R), Stat5 (N714F), NPM1, tel-jak2a, AML1-ETO, FLt3-ITD, FLT3-TKD (D835Y), MYCN, or MOZ/TIF2 expression." (PMID 26064935, 2015). "However, the prognostic significance of NPM1 in other myeloid neoplasms remains unknown as well as the best therapy for these patients." (PMID 38398096, 2024). "Of interest, NPM1-mutated AML patients who obtain long-term MRD-negative CR, but returning to a clonal hematopoiesis status, e.g., with persistent DNMT3A gene mutation, could be predisposed to development of a second different myeloid neoplasm." (PMID 33255988, 2020). "Notably, cases with loss of NPM1 mutation at disease reoccurrence were initially considered as secondary therapy-related myeloid neoplasms rather than true relapses from the previously found NPM1-mutated leukemic clone." (PMID 30404199, 2018). "This review aims to summarize the role of NPM1 in normal cells and in human cancer and discusses its current role in clinical management of AML and related myeloid neoplasms." (PMID 35054502, 2022). "In contrast, none of the three NPM1 myeloid neoplasm patients who received upfront induction chemotherapy developed AML." (PMID 40421449, 2025).
myeloid neoplasm (continued). "This in vitro “nononcogene addiction” of the S34F mutation to NPM1 is validated by human patient data demonstrating that U2AF1 and NPM1 mutations are mutually exclusive in myeloid malignancies." (PMID 33137094, 2020). "Interestingly, genes commonly mutated in AML and other myeloid neoplasms, such as FLT3, NPM1, KIT, RUNX1, and DNMT3A, were absent in our cohort." (PMID 40526100, 2025).